TLR4 (toll like receptor 4)
Diseases named in the same sentence as TLR4 in open-access papers (continued):
Sharing a sentence is not in itself a finding about the gene and the disease.
aspergillosis (8 papers, 2010 to 2024). Aspergillosis is an infection, growth, or allergic response caused by the Aspergillus fungus. "TLR4 recognizes O-linked mannan from Candida albicans, and human studies have linked Asp229Gly TLR4 polymorphism with susceptibility to bloodstream candidiasis and pulmonary aspergillosis." (PMID 24302927, 2013). "Additionally, increased susceptibility to aspergillosis has been observed in hematopoietic stem cell transplant patients with gene variants in TLR4, plasminogen, PFKFB3 polymorphisms, and other genetic factors." (PMID 39728022, 2024). "A Dectin-1 polymorphism resulting in an early stop codon was associated with reduced β-glucan binding and increased susceptibility to Candida albicans infections, whereas TLR4 polymorphisms correlate with susceptibility to aspergillosis in recipients of stem cell transplants." (PMID 20617171, 2010). "Of note, several polymorphisms of human TLRs, e.g., TLR1, TLR2, TLR4, TLR6, or TLR9, have been associated with increased risk of invassive aspergillosis in susceptible hosts." (PMID 29081774, 2017). "Several researchers have shown a significant association between TLR4 and/or TLR9 SNPs and the incidence of several forms of aspergillosis; however, another study failed to associate these polymorphisms with that disease." (PMID 25266752, 2014). "In pulmonary aspergillosis, TLR2 and TLR4 have no role in immunocompetent animals, although TLR2−/−and TLR4−/− are susceptible to invasive aspergillosis induced in immunosuppressed mice." (PMID 23255875, 2012). "In pulmonary aspergillosis, TLR2 and TLR4 have no role in otherwise immunocompetent animals, although Aspergillus CFU were elevated in vinblastin- or cyclophosphamide-treated TLR2−/−and TLR4−/− mice." (PMID 20617171, 2010).
Behçet's disease (8 papers, 2008 to 2024). "The results suggest that upregulated TLR4 is associated with HO-1 reduction in PBMCs from patients with Behçet's disease, leading to augmented inflammatory responses." (PMID 18234118, 2008). "TLR4 gene polymorphisms were also found to be associated with Behcet’s disease." (PMID 34468896, 2021). "TLR4 gene polymorphisms were found to be associated with Behcet’s disease, but not TLR2 Arg753Gln polymorphism." (PMID 27031066, 2016). "Levels of expression of HO-1 mRNA were significantly reduced in PBMCs from patients with active Behçet's disease, whereas those of TLR4, but not TLR2, were increased in PBMCs, regardless of disease activity." (PMID 18234118, 2008). "Moreover, in the limited clinical studies conducted thus far, zinc supplementation did not result in a reduction in TLR-4 gene expression in neonates or in patients with Behçet's disease." (PMID 40071246, 2024).
cerebral edema (8 papers, 2016 to 2025). "Targeting the TLR4/NF-κB signaling pathway represents a promising strategy to reduce neuroinflammation and cerebral edema, as this pathway is activated by DAMPs to drive pro-inflammatory factor expression." (PMID 41451367, 2025). "Activation of toll-like receptor-4 (TLR4) on neutrophils activates NET formation after TBI, which correlates with higher intracranial pressure (ICP), suggesting that neutrophils cause cerebral edema by NET production." (PMID 36873885, 2023). "Systemic inflammation can facilitate onset of hypoxic cerebral edema through interaction of astrocyte and microglia by activation of TLR4 and CRH/CRHR1 signaling." (PMID 26968975, 2016). "In addition, the botanical metabolite verbenalin reduces acute inflammatory injury and cerebral edema in intracerebral hemorrhage by inhibiting TLR4." (PMID 41451367, 2025). "In addition, diacerein ameliorates hyperammonemia induced cerebral edema and maintains BBB integrity through modulation of TLR4/AQP4/MMP-9 axis." (PMID 39556255, 2024).
Chlamydia infection (8 papers, 2010 to 2023). "It is unlikely to be Chlamydia hsp60, which has previously been implicated in TLR4 signalling during Chlamydia infection." (PMID 27021640, 2016). "PKR has previously been reported to contribute to the induction of interferon-β transcription during TLR4 stimulation of macrophages and our findings with Chlamydia infection are in agreement with this." (PMID 27021640, 2016). "In summary we have demonstrated a novel mechanism of PKR activation in response to Chlamydia infection, which requires TLR4 and IRE1α and that PKR enhances inflammatory responses." (PMID 27021640, 2016). "This suggests that TLR4/IRE1α mediated PKR activation enhances type-1 interferon response following Chlamydia infection and indicates that the role of PKR during infection is one of regulating inflammatory, rather than translational responses." (PMID 27021640, 2016). "TLR9—as already mentioned, most of the studies assessing host genetic determinants of Chlamydia infections are focusing on the extracellular TLR2's and TLR4's contribution to the differences in the susceptibility and severity of the infection." (PMID 23781508, 2013). "Several studies showed that SNPs in TLR4 have a role in making women more prone to subfertility as a late complication of Chlamydia infection." (PMID 23781508, 2013). "Prostate epithelial cells are thought to be early sensors of infection and CD14 and toll-like receptor 4 (TLR4) production in these cells contributes to protection from Chlamydia infection." (PMID 20070897, 2010). "It has been reported that TLR4 plays essential roles in the recognition of Chlamydia infection." (PMID 33343522, 2020). "Furthermore, we found that Chlamydia infection-induced IRE1α activation was dependent on TLR4 signalling as XBP-1 splicing was reduced in the presence of a TLR4 blocking antibody, and similar results were obtained with LPS as a control." (PMID 27021640, 2016). "The innate response upon Chlamydia infection of EEC is mediated by Toll-like receptor 4 (TLR4)." (PMID 24959205, 2014). "During chlamydia infection TLRs found on immune cells particularly TLR2, TLR4 and TLR9 which are important in recognizing and sensing chlamydia, are highly expressed in the female genital tract where they mediate immune cell response to chlamydia." (PMID 31388084, 2019). "We also report the interesting, but paradoxical observation that activation of the integrated stress response (ISR) resulting in CHOP expression as a consequence of Chlamydia infection was independent of TLR4 and by extension, the eIF2α kinase PKR." (PMID 27021640, 2016). "We have also demonstrated that activation of the ISR following Chlamydia infection occurs through the eIF2α kinase GCN2, presumably due to reduced amino acid availability, and is independent of TLR4, IRE1α, PKR and PERK." (PMID 27021640, 2016). "Chlamydia infection resulted in increases in transcript levels of KC and MIP-2 to similar levels in the lungs of Wt and TLR2−/−, but not TLR4−/− or 2/4−/− mice, throughout the time course." (PMID 22724018, 2012). "Given that we have provided evidence that CHOP induction was independent of PERK and TLR4 induced PKR activation, we tested the hypothesis that CHOP induction in response to Chlamydia infection occurs through activation of the amino acid responsive eIF2α kinase GCN2." (PMID 27021640, 2016).
chlamydial infection (8 papers, 2006 to 2025). "Most immunological studies, conducted primarily on mouse models, have shown that TLR2 and TLR4 activation and signalling strongly influence the elimination of chlamydial infection and the prevention of immunopathological sequelae." (PMID 39614880, 2024). "And the involvement of TLR2 and TLR4 in the initiation of immune cell activation and immunological response in chlamydial infections were demonstrated in several studies." (PMID 35693111, 2022). "Deficiency of TLR2 or TLR4 in macrophages significantly reduces TNF-α levels during chlamydial infection,while deficiency of TLR3 in epithelial cells increases its levels at the early stage of chlamydial infection." (PMID 34093528, 2021). "Although most immunological studies have been limited to mouse models, there is strong evidence to suggest that TLR2 and/or TLR4 activation and signaling has a strong influence on the clearance of the development of immunopathological sequelae as a result of chlamydial infection." (PMID 25799012, 2015). "Interestingly, it sometimes happens, even in chlamydial infection, that in the presence of TLR2 or TLR4 deficiency in macrophages, there may be a decrease in TNF-α levels." (PMID 40647668, 2025). "However, TLR2, and not TLR4 appears to be important for the initial signaling pathway for proinflammatory cytokine production during chlamydial infection." (PMID 16995947, 2006).
dilated cardiomyopathy (8 papers, 2013 to 2025). Cardiomyopathy which is characterized by dilation and contractile dysfunction of the left and right ventricles. "TLR4 upregulation in cardiomyocytes is also implicated in a mouse model of doxorubicin-induced dilated cardiomyopathy." (PMID 37239362, 2023). "Studies have shown the TLR4 activation induces proinflammatory cytokines, which is seen in dilated cardiomyopathy, and a positive correlation between TLR4 and enterovirus RNA in endomyocardial biopsy tissues." (PMID 31117206, 2019). "TLR2 and TLR4 have been shown to play a role in the pathogenesis of dilated cardiomyopathy." (PMID 38140398, 2023). "However, the role of mitochondrial dynamics in TLR4 activation-mediated dilated cardiomyopathy (DCM) progress remains unknown." (PMID 30046376, 2018). "In another study, dapagliflozin treatment was shown to elicit positive effects on doxorubucin-induced dilated cardiomyopathy by inhibiting NLRP3 inflammasome, decreasing p38-dependent toll-like receptor 4 (TLR4) expression." (PMID 40143092, 2025).
dysplasia (8 papers, 2014 to 2025). A usually neoplastic transformation of the cell, associated with altered architectural tissue patterns. "We previously showed that TLR4 expression increased in the Barrett metaplasia-dysplasia-carcinoma sequence." (PMID 33686512, 2021). "The expression of TLR4 was similar between intestinal metaplasia, low- and high-grade dysplasia and adenocarcinoma." (PMID 27008696, 2016). "Expression of TLR4 increased with increasing degrees of oral epithelial dysplasia and distribution of TLR4 extended from the basal layer through the stratum spinosum as dysplasia progressed." (PMID 25309546, 2014). "Furthermore, P. anaerobius interacts with TLR2 and TLR4 to increase intracellular levels of reactive oxidative species leading to cell proliferation, intestinal dysplasia, and CRC progression." (PMID 35884445, 2022). "We have previously shown that both TLR2 and TLR4 were expressed in normal squamocellular oesophageal epithelium, and expression increased in Barrett’s metaplasia-dysplasia-adenocarcinoma sequence, but their participation in oesophageal inflammation is unconfirmed." (PMID 33686512, 2021).
endophthalmitis (8 papers, 2013 to 2025). An infectious process affecting the internal structures of the eye. "Together, these findings demonstrated that inhibition of the TLR2 and TLR4 pathways and infection with SlpA-deficient B. thuringiensis in experimental endophthalmitis had a similar outcome." (PMID 32117322, 2020). "TLR-4 is a significant contributor to the intraocular inflammatory response seen in endophthalmitis." (PMID 40563988, 2025). "Fifteen genes upregulated 5-fold or higher following infection were associated with TLR4-induced inflammation, demonstrating that B. cereus is capable of activating TLR4 in a mouse model of endophthalmitis." (PMID 32331252, 2020). "To identify novel, targetable host inflammatory factors in this disease, we performed microarray analysis to detect TLR4-dependent changes to the retinal transcriptome during B. cereus endophthalmitis." (PMID 29661181, 2018). "TLR2 and TLR4 are key mediators of the innate immune response to bacterial pathogens during the early stages of endophthalmitis." (PMID 29661181, 2018). "We reported that Toll-like receptor 4 (TLR4) contributes to the robust inflammatory response to B. cereus during endophthalmitis and identified a cohort of TLR4-dependent inflammatory mediators that are upregulated in the retina 4 h following B. cereus infection." (PMID 32331252, 2020). "Here, we investigated whether inhibition of both TLR2 and TLR4 activation affected bacterial growth during experimental endophthalmitis." (PMID 32117322, 2020). "This suggests that SLP is a potent stimulator of both TLR2 and TLR4 innate pathways, and may contribute to the production of inflammatory mediators during experimental endophthalmitis." (PMID 32117322, 2020). "Future studies will evaluate the retinal and global ocular inflammatory responses over the course of B. cereus endophthalmitis to identify pathway-based anti-inflammatory targets, specifically, those that are regulated by TLR4, and to identify the B. cereus produced or induced ligand for TLR4." (PMID 29661181, 2018). "We have previously reported that during endophthalmitis progression, Bc stimulates activation of both TLR2 and TLR4 pathways, resulting in signal cascade initiation through both MyD88-dependent and MyD88-independent (TRIF-dependent) pathways, respectively." (PMID 38106476, 2023). "Taken together, these results suggest a potential role for Bacillus SLP in host-bacterial interactions, as well as in endophthalmitis pathogenesis via TLR2- and TLR4-mediated pathways." (PMID 32117322, 2020). "Our findings demonstrate for the first time that Bacillus SLP impacted endophthalmitis pathogenesis by activating both TLR2 and TLR4 pathways." (PMID 32117322, 2020). "We demonstrated that during B. cereus endophthalmitis, TLR2 and TLR4 each directly influenced the severity of intraocular inflammation." (PMID 32117322, 2020). "In the current study, PlyB did not activate TLR2 or TLR4, TLRs that impact B. cereus endophthalmitis pathogenesis." (PMID 37273201, 2023). "In addition to identifying SLP as an unexpected TLR4 agonist, we revealed for the first time that inhibiting SLP-mediated TLR2/4 activation in experimental endophthalmitis could reduce disease severity." (PMID 32117322, 2020). "During B. cereus endophthalmitis, the absence of TLR2 and TLR4 in mice resulted in less infiltration of PMNs and fibrin accumulation, and preserved retinal architecture." (PMID 32117322, 2020).
hematoma (8 papers, 2012 to 2022). A hematoma is a collection of blood from a vascular structure into an extravascular space. "Further studies have shown that TLR4 also inhibits the phagocytosis of microglia on the surface of red blood cells, resulting in hematoma absorption delay and severe neurological deficits in ICH patients." (PMID 34025674, 2021). "After hemolysis, hematoma components are released, inducing microglial activation via TLR4, which initiates the activation of transcription factors (such as NF-κB) to regulate expression of proinflammatory cytokine genes." (PMID 30498516, 2018). "Generally, at 3 days post injury, TLR4 expression was increased to peak in the epicenter, but TLR4 expression was in low level and microglia/macrophage remained resting in the hematoma area at the same time point." (PMID 24015844, 2013). "Upregulation of CD36 expression was demonstrated in TLR-4 knockout mice suggested that TLR-4 suppression could promote hematoma resolution 49,55." (PMID 35832077, 2022). "TLR4 is known to be activated by hematoma components and induce neuroinflammation following ICH." (PMID 33206327, 2021). "The consumption of BLVRA may contribute to activating microglia and resolving hematoma by translocating into the nucleus and inhibiting the TLR-4 promoter." (PMID 29678206, 2018). "Hematoma resolution could promote clearance of hemin, thus reducing hemin-mediated activation of TLR4 and subsequent inflammatory responses." (PMID 23414417, 2013). "Knockout of TLR4 results in upregulation of CD36 in the perihematomal region, suggesting that the TLR4 signaling pathway could play a role in hematoma resolution." (PMID 23414417, 2013).
Hypoglycemia (8 papers, 2018 to 2023). A decreased concentration of glucose in the blood. "LPS, or endotoxin, induces acute inflammatory challenge by binding to toll like receptor 4 (TLR4), initiating the signaling cascade that activates proinflammatory cytokines, and also leads to hypoglycemia." (PMID 37701898, 2023). "Also, TLR4 changes under hypoglycemia were comparable to those of control (normoglycemia) (p > 0.05)." (PMID 32806763, 2020). "The molecular mechanism via which labile heme induces hypoglycemia is not entirely clear but has been linked to signaling via Toll-like receptor 4 (TLR4), a PRR that senses labile heme." (PMID 30425714, 2018). "At hypoglycemia, TLR4:MD-2 complex and HSPA8 both decreased in T2D versus baseline (p < 0.05), with HSPA8 remaining significantly lower at hypoglycemia in T2D versus controls (p < 0.01)." (PMID 34831332, 2021). "At hypoglycemia, UBE2N, STIP1, and UBE2L3 increased (all p < 0.05), whilst TLR4:MD-2 and HSPA8 decreased (p < 0.05) in T2D versus baseline." (PMID 34831332, 2021). "Details of the response of the TLR4:MD-2 complex have not been reported before in hypoglycemia because, whilst the proteomic technology was the same, the proteomic panels differed slightly." (PMID 34831332, 2021). "TLR4:MD-2 complex was elevated in T2D and fell at hypoglycemia, although it did not return to baseline levels by 24-h." (PMID 34831332, 2021). "Whether heme sensing by TLR4 mediates the development of hypoglycemia during polymicrobial sepsis was not established." (PMID 30425714, 2018).
Infertility (8 papers, 2009 to 2025). "TLR4 has been localized in the human epididymis and prostate, where it can activate the inflammatory response and ultimately leads to temporary or persistent infertility." (PMID 32064024, 2020). "Although the activation of TLR4, and the expression of IL-1β and TNF-α, provides an essential host immune defence mechanism, they are also involved in different aspects of infertility." (PMID 32064024, 2020). "However, this seems unlikely as infertility has not been reported for Tlr4−/− mice." (PMID 20877575, 2010).
irritable bowel syndrome (8 papers, 2019 to 2025). Irritable bowel syndrome (IBS) is a chronic functional condition of the lower gastrointestinal (GI) tract characterized by abdominal pain or discomfort and disordered bowel habit (diarrhea, constipation, or fluctuation between the two). "Prevotella contributes to inflammation by producing lipopolysaccharide (LPS), which can trigger Toll-like receptor 4 (TLR-4), leading to low-grade inflammation and diarrhea-predominant irritable bowel syndrome (IBS)." (PMID 38248533, 2024). "Repeated water avoidance stress (WAS) induces visceral allodynia and colonic hyperpermeability via toll-like receptor 4 (TLR4) and proinflammatory cytokine pathways, which is a rat irritable bowel syndrome (IBS) model." (PMID 31689935, 2019).